LRP1 (LDL receptor related protein 1)
Diseases named in the same sentence as LRP1 in open-access papers (continued):
Sharing a sentence is not in itself a finding about the gene and the disease.
tumor (continued). "Moreover, LRP1 expression was independent of other prognostic markers (large tumor size, microvascular invasion, and multiple tumors) for both OS and cumulative recurrence." (PMID 22427881, 2012). "However, the detection of LRP-1 and survivin expressions mainly depends on tissue sampling, which is limited by the invasiveness of the operation and may not reflect the entire tumor." (PMID 36106114, 2022). "However, low LRP1 IHC tumor score was not predictor for PFS in these patients." (PMID 29507659, 2018). "Moreover, it has been established that eHSP90 binds the extracellular sub-domain II of LRP-1 and activates downstream AKT1 and AKT2 kinase signaling pathways through the cytoplasmic NPVY motif of LRP-1, thus promoting cell motility and being essential for wound healing as well as tumor invasion." (PMID 25629807, 2015). "Similarly, many cancer cells are characterised by an ability to grow in low levels of growth hormone, so it was of interest to examine LRP1 expression in cells grown under general serum-deprived conditions, although not strictly an exact replica of in-vivo conditions near a tumour." (PMID 22027709, 2011). "Importantly, DS exhibited no tumor growth-suppressive effects in mice bearing LRP1KO MC38 cells, highlighting the essential role of LRP1 in DS-mediated tumor growth inhibition." (PMID 40625660, 2025). "In the present work, we investigated whether LRP-1 may control DDR1 expression at the plasma membrane in non-invasive CRC and influence its ability to regulate tumor cell proliferation upon its activation by type I collagen." (PMID 32582700, 2020).
cancer (168 papers, 2009 to 2026). A tumor composed of atypical neoplastic, often pleomorphic cells that invade other tissues. "These included proteins associated with cancer cell biology and/or metastasis, such as LRP1, and MUC1." (PMID 39020428, 2024). "We examined the RNA expression levels of LRP1 across various malignancies and their corresponding normal tissues to understand the association between LRP1 and different cancer types." (PMID 39063239, 2024). "Evidence shows that LRP1 is highly expressed in multiple types of cancers and is closely associated with cancer metastasis." (PMID 37842093, 2023). "Adhesion assays were also conducted to demonstrate that PKA activity was functionally associated to the control of carcinoma cell attachment and spreading by LRP-1-mediated regulation of calpains." (PMID 36052226, 2022). "TSP1 is associated with EVs released by cancer-associated fibroblasts via a complex that includes LRP1 and annexin A6." (PMID 33925464, 2021). "Lower expression of LRP1 is associated with the aggressive phenotypes and inferior clinical outcomes in some cancers." (PMID 33777800, 2021). "The profile revealed that LRP1 was mutated and functioned as a cancer driver in about 28.6% of cases." (PMID 32098350, 2020). "LRP-1 was shown to decrease talin levels and distribution in cancer cells and is required for paxillin and FAK association within focal adhesions." (PMID 29108253, 2017). "In this cancer, high levels of LRP1 mRNA expression were associated with decreased survival in the 50%/50% comparison (p<0.0001) and in the 25%/25% comparison (p<0.0005)." (PMID 29088295, 2017). "Only by understanding the mechanisms of these effects can we develop novel diagnostic and therapeutic strategies for cancers mediated by LRP1." (PMID 26738504, 2016). "LRP-1 is known to bind more than 40 different ligands, and has been implicated in various pathologies including cancer/metastasis." (PMID 23675525, 2013). "Although a growing number of studies have demonstrated that LRP1 is implicated in cancer progression, its precise role and potential underlying mechanism in specific cancers remain contentious." (PMID 22427881, 2012). "We also assessed the association between ICGs and LRP1 expression in 39 types of cancer." (PMID 39063239, 2024). "Additionally, LRP1’s involvement in cytokine–cytokine receptor interactions, intricately linked with immune reactions and cancer prognosis, underscores its broader biological significance." (PMID 39063239, 2024). "Notably, high LRP1 expression was associated with decreased B cell infiltration and increased infiltration of other immune cell types in specific cancers." (PMID 39063239, 2024). "Although several studies have reported that a low level of LRP1 was associated with the aggressive phenotype of certain types of cancer, other studies have demonstrated that upregulation of LRP1 expression was observed in the progression of certain types of malignancy." (PMID 36703790, 2022). "Here, we summarized recent studies showing the involvement of fibrinolytic factors, such as uPA, tPA, PAI-1, and PAI-2, and associated receptors, such as uPAR and LRP1, in modulating critical signaling pathways, and thereby contributing to the hallmarks of cancer." (PMID 33669052, 2021). "LRP1B, a close homolog of LRP1, is among the top 10 significantly mutated genes in human cancer." (PMID 32850302, 2020). "The tissue and cancer related expression of LRP1 and its alternative splice variant smLRP1 might add a new aspect to this controversy." (PMID 28662213, 2017). "Thus, there are multiple opportunities to develop new LRP1-related diagnostic and therapeutic approaches for many types of cancers." (PMID 26738504, 2016).
cancer (continued). "Only a few LRP1 polymorphisms or mutations were identified in cancer specimens." (PMID 26617523, 2015). "Many of the 12q fusion genes produced chimeric proteins or disrupted cancer-associated genes such as RUNX2, CCND3, and LRP1, indicating that some of the fusions may contribute to cancer progression independently of MDM2/CDK4 co-amplification." (PMID 25300797, 2014). "LRP1 also regulates cell surface expression of matrix receptors by modulating both extracellular and intracellular signals, though current knowledge of the underlying mechanisms remains partial in the frame of cancer cells interaction with matricellular substrates." (PMID 36052226, 2022). "Further analysis revealed that MDK and NCL/PTPRZ1/LRP1 were highly expressed in cancer cells and astrocytes/cancer cells/macrophages in the MDK signaling pathway, respectively." (PMID 40527884, 2025). "PAI-1 suppresses the abscopal effect of radioimmunotherapy by inducing the differentiation of pericytes into SERP2 high-expressing CAFs via the LRP1/p65 signaling pathway in multiple human and murine cancer types." (PMID 41008624, 2025). "Collectively, our findings establish LRP1 as a novel therapeutic target for cancer immunotherapy and highlight DS-driven immune reprogramming as a translatable strategy to potentiate ICB efficacy." (PMID 40625660, 2025). "This ability of MDK to promote M2 polarization and macrophage infiltration has been demonstrated in several cancers, with several putative receptors being identified including LRP1, Notch2, and syndecan 3 (SDC3)." (PMID 40429950, 2025). "To determine the relationship between LRP1 and stromal cells in cancer, we analysed the stromal score." (PMID 39063239, 2024). "To better understand the potential mechanisms of LRP1 in cancer, we performed a functional enrichment analysis based on the high and low expressions of LRP1." (PMID 39063239, 2024). "For CD8+ T cells, LRP1 showed positive correlations in six cancer types: OC (r = 0.263, p < 0.001), BLCA (r = 0.280, p < 0.001), GBM (r = −0.341, p < 0.001), KIRP (r = 0.511, p < 0.001), THCA (r = 0.176, p < 0.001), and LGG (r = 0.111, p < 0.001)." (PMID 39063239, 2024). "We next examined the association between LRP1 and various factors, such as prognostic value and mRNA gene expression, using Oncomine, GEPIA, TNM, Sangerbox3, CancerSEA, and pan-cancer analyses." (PMID 39063239, 2024). "Although the role of immune infiltration in cancer prognosis is well-documented, there is a paucity of research exploring the relationship between LRP1 and immune infiltration in OC." (PMID 39063239, 2024). "Beyond its well-established physiological roles, emerging evidence has highlighted the role of LRP1 in the complex landscape of cancer biology." (PMID 39063239, 2024). "The PAI-1/LRP1/uPAR complex also stimulates the migration and polarization of monocytes and immunosuppressive macrophages in cancer." (PMID 38779680, 2024). "Using the Oncomine, GEPIA, and TIMER databases, we explored LRP1 expression across various cancer types, revealing high LRP1 expression in numerous cancers, including OC." (PMID 39063239, 2024). "There were strong connections via the GAS6-AXL/MERTK and THBS1-CD36/CD47/ITGA4/ITGB1/LRP1 axes between cancer cells (contributing ligands) and TAMs (contributing receptors)." (PMID 38169544, 2024). "To further assess the prognostic significance of LRP1 across different cancer types, we performed a forest plot analysis to examine its expression and its impact on OS across 39 cancer types using a Cox regression model." (PMID 39063239, 2024). "Initially, we utilised the TCGA databases to compare LRP1 mRNA levels in 26 cancer types with those in normal tissues." (PMID 39063239, 2024). "LRP1 has been found to influence cancer progression and metastasis by regulating cell migration, adhesion, proliferation, and the modulation of the TME." (PMID 39063239, 2024).
cancer (continued). "A growing amount of evidence has strengthened the putative role of LRP-1 in crucial events during cancer progression by promoting cell migration and invasion, in addition to cell survival." (PMID 37372056, 2023). "LRP1 promotes cancer cell migration and invasion by regulating matrix metalloproteinase (MMP) expression and inhibits apoptosis by regulating the caspase and insulin receptor signaling pathway." (PMID 37239055, 2023). "Recent studies have shown the prognosis-related role of LRP1 in various types of cancer, including BLCA." (PMID 37153545, 2023). "Mara Brancaccio (University of Torino, Italy) recently discovered that Morgana is released from cancer cells and in association with extracellular Hsp90 induces cancer cell migration via Toll-like receptors TLR2, TLR4 and LRP1." (PMID 36602710, 2023). "Lactoferrin can specifically bind with low‐density lipoprotein receptor‐related protein 1 (LRP‐1) overexpressed on the surface of cancer cells and macrophages." (PMID 36599655, 2023). "According to Human Protein Atlas, LRP1 in general has low cancer specificity to conclude that more studies are necessary to properly evaluate LRP1’s role in cancer." (PMID 37020553, 2023). "Regarding the controversy over the function of LRP1 in the invasiveness of cancer cells, we tested two antagonistic ligands, bLF and tPA, in order to gain insight into the detailed mechanism of LRP1 in OSCC cell invasion." (PMID 36839884, 2023). "In contrast, inhibition of LRP1 expression in thyroid cancer intensifies the invasion ability of cancer cells to metastasize to lymph nodes and lungs." (PMID 37020553, 2023). "Meanwhile, a previous study reported that LRP1 was involved in cancer cell migration and invasion, which was consistent with our findings." (PMID 37842093, 2023). "It is worth noting that LRP1 is a multifunctional receptor that has been shown to be involved in the pathological processes of cancer." (PMID 37310025, 2023). "So far, several other proteins (TLRs and EGFRs) binding to eHSP90α have been reported, but LRP1, as the receptor of eHSP90α, is still mainly studied in cancer metastasis." (PMID 35628341, 2022). "This work identified a cluster of co-mutation genes (LRP1, ACVR2A, and SETBP1) and found these genes were significantly associated with a family history of cancer." (PMID 35814400, 2022). "LRP1 is a ubiquitous cell-surface receptor that mediates hypoxia-induced cell migration, cancer cell survival, and epithelial-to-mesenchymal transition." (PMID 36291096, 2022). "Several studies have reported that, upon binding with LRP1, secreted HSP90α promotes the migration and invasion of various cancer cells through NF-κB, PI3K/AKT, or the MAPK-dependent pathway." (PMID 35628341, 2022). "Having identified calpains as new intracellular targets regulated by LRP-1 in carcinoma cells, we next set up an experimental design to decipher the mechanistic nature of the process controlling their activities." (PMID 36052226, 2022). "We evidenced that H-89 or KT5720 treatment respectively resulted in about a 2-fold and 1.7-fold increase of basal calpain activity in LRP-1 expressing carcinoma cells." (PMID 36052226, 2022). "We then conducted adhesion assays to test the likely involvement of LRP-1-dependent calpain regulation in the control of carcinoma cell attachment to matrix compounds." (PMID 36052226, 2022). "As expected, we observed that LRP-1 silencing reduced carcinoma cell migration by 29% as compared to migrated control cells." (PMID 36052226, 2022). "In accordance with previous reports, LRP-1 silencing induced drastic changes of carcinoma cells morphology and actin fibers distribution." (PMID 36052226, 2022). "We therefore demonstrated that LRP-1 maintains a low level of calpain activity that contributes to the migratory and invasive capacities of carcinoma cells." (PMID 36052226, 2022).
cancer (continued). "We showed that LRP1-mediated calpain inhibition participates in talin-positive focal adhesions dissolution and limits β1-integrin expression at carcinoma cell surface." (PMID 36052226, 2022). "The available data indicate that Morgana binds directly to TLR2, while it requires additional components, present in the cancer cell conditioned medium, to bind to LRP1." (PMID 34722515, 2021). "The main HSP-activated receptors involved in cancer progression are Low density lipoprotein receptor-related protein 1 (LRP1), Toll Like Receptors (TLRs), the EGF receptor family (ERBB) and cluster of differentiation 40 (CD40)." (PMID 33544155, 2021). "By activating the MEK/ERK pathway and concomitantly inhibiting MKK7/JNK, LRP-1 can regulate cancer cells anchoring to the ECM." (PMID 34680548, 2021). "A family of LRPs have been found to play a role in cancer pathophysiology, including LRP1, LRP2, and LRP10." (PMID 34281263, 2021). "Namely, the expression levels of MAOB and LRP1 were downregulated in cancer tissues compared with paracarcinoma tissues, and the expression of FASN was upregulated." (PMID 34819038, 2021). "Our data demonstrate that ESCC patients with concurrently high expression of PAI-1 by stromal cells and of LRP1 by either cancer cells or stromal cells including TAMs, or both have the shortest survival duration." (PMID 33311557, 2021). "Higher mutated frequency in Wnt signalling of pancreatic body/tail cancers mainly resulted from distinctly enriched SMAD4 mutations (P = 0.008), and more abundant LRP1/1B and CTNNB1 mutations." (PMID 33452856, 2021). "Consistent with the TCGA and GEO results, we also found that the expression levels of MAOB and LRP1 were downregulated in cancer tissues compared with paracarcinoma tissues, and the expression of FASN was upregulated." (PMID 34819038, 2021). "It has been well reported that cell surface receptor LRP1 transmits eHsp90α signal intracellularly to stimulate cell motility during wound healing and cancer invasion." (PMID 34299365, 2021). "A complex containing LRP1, TSP1, and annexin A6 was recently identified as being produced by cancer-associated fibroblasts in pancreatic ductal adenocarcinoma." (PMID 33925464, 2021). "Plasminogen-binding receptors, such as uPAR, ⍺-enolase, and a low-dose-lipoprotein, such as LRP1, have been proposed to mitigate resistance to cancer therapy." (PMID 33669052, 2021). "LRP1 expression levels are often downregulated in cancer and some studies consider low LRP1 expression levels to be a poor prognostic factor." (PMID 32098350, 2020). "We postulated that hemopexin present in the stroma of PDAC binds to LRP1 on the cancer-cell membrane, thereby promoting invasion by activating the mitogen-activated protein-kinase pathway and the NF-κβ pathway." (PMID 32663208, 2020). "The use of the AFM, conducted on the FTC-133 human thyroid carcinoma cell line, demonstrated the LRP-1 induced phenotypic changes in cancer cells." (PMID 33233645, 2020). "In cancer, LRP1 was suggested to play a dual role in cell invasion and migration, depending on the specific cell type and their microenvironment." (PMID 32245111, 2020). "Targeting the low-density lipoprotein receptor-related protein 1 (LRP-1) is considered a promising therapeutic target as LRP-1 can internalize the proteases involved in cancer progression." (PMID 33233645, 2020). "T2 specific variants were enriched in the cancer metastasis signaling (P = 4.33E‐03) including the matrix metalloproteases 11 (MMP11), low density lipoprotein receptor‐related protein 1(LRP1), mutS homolog 3 (MSH3), and son of sevenless homolog 2 (SOS2)." (PMID 30941903, 2019). "ANG1005 crosses the blood-brain barrier and enters the cancer cells via receptor-mediated transcytosis of the low-density lipoprotein receptor-related protein 1 (LRP1), which is upregulated in some cancers." (PMID 35582143, 2019).